ABCB1 (ATP binding cassette subfamily B member 1)
Diseases named in the same sentence as ABCB1 in open-access papers (continued):
Sharing a sentence is not in itself a finding about the gene and the disease.
breast carcinoma (continued). "Pimozide, an FDA-approved psychotropic drug, inactivated STAT5a and downregulated the expression of ABCB1, thus sensitizing MCF7/DOX cells to DOX in vitro and in vivo, providing a promising strategy for treating patients with chemoresistant breast cancer in the clinic." (PMID 34336684, 2021). "Statistical analysis showed that patients with ABCB1-positive breast cancer had a significantly lower pCR rate than those with ABCB1-negative breast cancer." (PMID 34336684, 2021). "Since P-glycoprotein (Pgp; ABCB1; MDR1) is one of the leading transporters and expressed in various breast cancer cell lines, an effective drug delivery system with a unique mechanism of drug transport across the cancer cells might overcome the MDR." (PMID 33080962, 2020). "By DNA methylation analysis of the ABCB1, ABCC1, and ABCG2 promoters in three breast cancer cell lines (MCF7, luminal A subtype; ZR-75-1, luminal B subtype; MDA-MB-231, triple negative subtype), the ABCC1 promoter has been found to be unmethylated in each of the cell lines." (PMID 33066132, 2020). "Interestingly, recent studies have shown promoter translocations to be common drivers of ABCB1 expression in recurrent, chemotherapy-treated high-grade serous ovarian (HGSC) and breast cancer." (PMID 33167906, 2020). "Amongst the HGSC and breast cancer samples, overall 15 fusions involving addition of non-coding exons 5′ from the partner gene to exon 2 of ABCB1 were identified." (PMID 30894541, 2019). "LC–MS/MS results showed a reduction in the protein levels of ABCA8, ABCB1, and ABCG2; hence, we examined whether sulbactam can inhibit the mRNA expression of ABC transporters in the human breast cancer cells in the presence of doxorubicin." (PMID 30202239, 2018). "Our studies offer a novel strategy to solve taxane resistance in breast cancer, including TNBC—that is, the combination of taxane treatment and the adjuvant pharmacological inhibition of ABCB1 may greatly improve the chemotherapeutic efficacy in breast cancer." (PMID 30052635, 2018). "Because FTH1P3 and ABCB1 are both up‐regulated in paclitaxel‐resistant breast cancer cells, we could conclude that miR‐206 targets simultaneously with FTH1P3 and ABCB1." (PMID 29971911, 2018). "Multidrug resistant (MDR) proteins, ABCB1 and ABCG2 are breast cancer resistance genes." (PMID 29187162, 2017). "In the present study, we demonstrated that genetic variants of the host, such as SNPs of MAP3K1, CYP2B6, UGT1A1, HCN1, ABCB1, and ALDH3A1, may worse the prognosis of HR-positive breast cancer patients, predominantly for premenopausal women." (PMID 28178648, 2017). "In conclusion, this study found that ABCB1 C3435T and ABCG2 C421A genotypes were not significantly correlation with the susceptibility to breast carcinoma in a Chinese Han population." (PMID 29340035, 2017). "In conclusion, in-house developed bisulfite PSQ methods were applied to determine the promoter methylation status of ABCB1, ABCC1 and ABCG2 in 19 human cancer cell lines, MDR cell models as well as tumor, tumor-adjacent and tumor-distant tissues from 16 breast cancer patients." (PMID 27689338, 2016). "Nonetheless, it is worth noting that in a human breast cancer cell line the hAFS-CM did not modulate ABCB1 levels or Dox efflux, indicating that, at least in some tumour cell types, Dox metabolism is not enhanced by hAFS-CM." (PMID 27444332, 2016). "Our data suggest that both ABCB1 and ABCC11 are involved in the development of eribulin resistance in breast cancer cells and that eribulin or its metabolites might be substrates of ABCB1 and ABCC11." (PMID 27588398, 2016).
breast carcinoma (continued). "Our results of cumulative analyses further emphasize the importance of changes that occur simultaneously in cellular transport (p.Ser893Ala/Thr in ABCB1, c.-24C>T in ABCC2) and DNA repair systems (p.Lys751Gln in ERCC2) for the outcome of treatment in breast cancer patients." (PMID 27527855, 2016). "To confirm that both ABCB1 and ABCC11 were able to confer resistance to eribulin in breast cancer cells, we tested whether transient overexpression of ABCB1 or ABCC11 would alter the sensitivity to eribulin in HEK293T cells." (PMID 27588398, 2016). "In addition, we investigated if aberrant promoter methylation levels of ABCB1, ABCC1 and ABCG2 occur in tumor and tumor-surrounding tissues from breast cancer patients." (PMID 27689338, 2016). "Our results suggest that ABCB1 and ABCC11 may be used as biomarkers for predicting the response to eribulin in patients with breast cancer." (PMID 27588398, 2016). "We determined the methylation patterns in tumor, tumor-adjacent and tumor-distant tissues from the same breast cancer patients in order to investigate if aberrant promoter methylation levels of ABCB1, ABCC1 and ABCG2 can be used as indicator for detection of field cancerization in breast cancer." (PMID 27689338, 2016). "Besides, Wnt5A expression level was positively correlated with ABCB1 and VEGF expression levels in the clinical breast cancer tissues." (PMID 25401518, 2014). "The MCF-7 breast cancer cell line, used as positive control for the real-time PCR experiments, expressed ABCB1 (data not shown)." (PMID 24124770, 2013). "In this study, ABCB1 methylation was associated with non-proliferative, Ki67 negative tumours supporting a positive role for ABCB1 methylation in breast cancer progression and outcome." (PMID 20056007, 2010). "Additionally, the sponging of miR-221 via GAS5 has been demonstrated to mitigate Adriamycin resistance in breast cancer, specifically through the upregulation of Dickkopf 2 (DDK2) and suppression of P-glycoprotein (ABCB1) expression and the Wnt/β-catenin pathway." (PMID 39941145, 2025). "Thus, reduced expression of GAS5 in MDR breast cancer cells could upregulate Wnt/β-catenin signaling and induce the MDR transporter ABCB1 expression." (PMID 39403602, 2024). "The main efflux transporters involved in BC MDR are ABCB1 (also termed P-glycoprotein, P-gp, or MDR1), multidrug resistance protein 1 (MRP1/ABCC1) and ABCG2 (also termed breast cancer resistance protein BCRP or mitoxantrone resistance protein MXR)." (PMID 38877575, 2024). "In addition, the σ2 receptor ligands exhibited promising anti-tumor proliferative activity against breast cancer MCF-7/ADR cells and could inhibit the activity of ABCB1, suggesting that σ2 receptor ligands may be potential therapeutic agent in anti-tumor MDR." (PMID 36120340, 2022). "MCF7 breast cancer cells that are thought to survive treatment with ionizing radiation (MCF-7/IR6) showed a chemoresistance phenotype by expressing high levels of MDR1 (ABCB1) but not of MRP1 (ABCC1) or BCRP (ABCG2)." (PMID 35215350, 2022). "It has been reported that hyaluronan–CD44 interactions are capable of stimulating ABCB1 expression and activity through promoting ankyrin–cytoskeleton interactions, Nanog-Stat-3 signalling, ErbB2 signalling and PI3K/AKT-related survival pathways in breast cancer cell lines." (PMID 33801148, 2021). "In adriamycin resistant MCF-7 cells and breast cancer tissues, decreased levels of the lncRNA GAS5 suppressed the expression of miRNA hsa-mir-221-3p, which relieves expression of the Wnt inhibitor DKK2, resulting in increased Wnt signaling and ABCB1 upregulation." (PMID 35582031, 2021). "Besides ABCB1 and EPHA3, we found that the annotation genes for the top 10 circRNAs in docetaxel-resistant breast cancer cells are involved in neuronal development, synaptic vesicle trafficking, histone-binding, and maintaining epithelial function via the PI3K/AKT signaling pathways." (PMID 34055636, 2021).
breast carcinoma (continued). "In addition, ABCB1 substrate drug vinblastine (VBL)- or trans-flupentixol (tFPT)-induced membrane ruffling is an early indicator of cellular motility and metastatic potential in ABCB1 overexpressing MCF7/AdrR and ABCB1 transfectant MCF7/BC-19 breast cancer cells." (PMID 33801148, 2021). "In addition, some studies point out that the up-regulation of EMT-associated transcriptional factors, containing Slug, Zeb1 and Twist1, can directly lead chemotherapy in breast cancer and NSCLC through the ATP-binding cassette (ABC) transporter family of proteins (ABCB1, ABCC1 and ABCG2)." (PMID 33282725, 2020). "The role of the ATP-binding cassette (ABC) transporters in tumorigenesis of White breast cancer patients is further supported by the enrichment of the “brown” module in basal transcription factors, including the ATP-binding cassette subfamily members ABCA9, ABCC9, ABCG2, ABCB1, ABCA6, and ABCA8." (PMID 32873298, 2020). "Moreover, we discovered that KRT19 regulates CSC reprogramming and drug sensitivity in breast cancer and cancer stem cell-like cells, through mediating stemness (NANOG, OCT4, KLF4, and SOX2) and drug-resistant (ALDH1, ABCG2, ABCC1, and ABCB1) marker expression." (PMID 29747452, 2018). "However, the effects of CSBAs are not exported by ABCB1, and thus their toxicity should not be affected by the high ABCB1 expression in taxane-resistant breast cancer cells including MCF-7TXT." (PMID 28787019, 2017). "Interestingly, no modulation of the multidrug resistance gene ABCB1 nor Dox fluorescence in culture medium was observed when the human breast cancer cell line MDA-MB-23121, was pre-incubated with hAFS-CMHypo before being treated with Dox." (PMID 27444332, 2016). "In this regard, Wnt5a was also found to modulate cell cycle progression and contributes to the chemoresistance in pancreatic cancer cells and regulates ABCB1 expression in multidrug-resistant breast cancer cells through activation of the noncanonical PKA/beta-catenin pathway." (PMID 27895670, 2016). "Thus, ABCB1 and ABCC11 expression may be used as a biomarker for predicting the response to eribulin in patients with breast cancer." (PMID 27588398, 2016). "In the present study we aimed to enlarge the database by determining the promoter methylation patterns of ABCB1, ABCC1 and ABCG2 in cancer cell lines derived from different types of cancer, MDR cell models as well as tumor, tumor-adjacent and tumor-distant tissues from breast cancer patients." (PMID 27689338, 2016). "Further, we identified four novel genes (ABCB1, FOXC1, PPP2R2B and PTEN) that were found to be already aberrantly methylated in DCIS (Ductal carcinoma in situ), a pre-invasive stage of breast cancer and that were also found to be methylated in the locally advanced breast cancers." (PMID 24093668, 2013). "The results revealed that the lncRNA EPB41L4A-AS2 was expressed in the parental breast cancer cell lines but was absent in the docetaxel-resistant descendants; the decreased level of EPB41L4A-AS2 was also significantly associated with an increased level of ABCB1 mRNA." (PMID 37569629, 2023). "Moreover, we also found that ITZ could not revert DTX resistance in the ABCB1-overexpressing DTX-resistant breast cancer cell line, MCF-7R." (PMID 35721223, 2022). "Hence, the expression pattern of ABCB1 and many other ABC transporters in breast tissue during gestation, lactation and even menopause may merit attention when evaluating the expression of these pumps in breast cancer." (PMID 33801148, 2021). "Given that ABC transporters might not be involved in hyaluronan translocation in breast cancer, whether the aberrant expression of ABCB1 occurs as a result of CD44 upregulation and whether ABCB1 and its SNPs alter the binding activity of CD44 need to be clarified in future studies." (PMID 33801148, 2021).
breast carcinoma (continued). "Here we report aberrant methylation levels of ABCB1, FOXC1, GSTP1, PPP2R2B and RASSF1A in DCIS and stage I-IV providing evidence that suggests that changes in methylation level is an early event and may also be important in progression to later stages of breast cancer." (PMID 24093668, 2013). "Although ABCB1 and ABCC1 are two of the most studied and cancer-related ABC transporters, there is a lack of studies analyzing their effect on AIC in breast cancer." (PMID 37367397, 2023). "VEGFA is also known to modulate cancer stem cell-enriched side population in breast cancer patients through non-canonical PKA/β-catenin pathway and ABCG2/ABCB1 drug efflux transporters." (PMID 35884426, 2022). "Quick literature search revealed that PTGS2, EGFR, ABCB1, and IL6 high expression rather than low expression was correlated with breast cancer growth." (PMID 32577155, 2020). "Only one of the ABC transporters family member, ABCB1, and CAR were found upregulated at mRNA levels in chemo-resistant sublines of breast cancer cells (data not shown)." (PMID 31097752, 2019). "In the present study, four SNPs of ABC transporter genes, namely ABCC1, ABCC2, ABCB1, and ABCG2, were screened in Jordanian Arabs with and without breast cancer." (PMID 31391850, 2019). "As cisplatin increased the canonical Wnt7b in the study, increase of ABCB1 and ABCG2 perhaps is not surprising as previous studies have also demonstrated beta-catenin dependent induction of ABCB1 in breast cancer and ABCG2 in colon cancer." (PMID 28340578, 2017). "Both ABCB1 and ABCC11 are involved in the development of eribulin resistance in breast cancer cells in vitro regardless of the breast cancer subtype." (PMID 27588398, 2016). "In the present study, upregulation of both ABCB1 and ABCC11 was observed in all seven breast cancer cell lines, regardless of their receptor status." (PMID 27588398, 2016). "In the present study, we demonstrated for the first time that ABCB1 and ABCC11 confer eribulin resistance in breast cancer cells regardless of their subtype." (PMID 27588398, 2016). "More precisely, in breast cancer cells, ABCB1 (P-glycoprotein), a multidrug resistance protein, is regulated by miR-19b despite the absence of miR-19b binding sites within the 3′UTR of ABCB1 mRNA." (PMID 35884580, 2022). "Hence, upregulation of both ABCB1 and ABCC11 in breast cancer cells was induced by continuous treatment regardless of the subtype of the cells." (PMID 27588398, 2016). "However, our results indicated that ABCB1 rs1045642 and ABCC1 rs3743527 did not influence the development of cardiotoxicity after anthracycline-based treatment in the studied group of patients with breast cancer." (PMID 37367397, 2023). "In conclusion, our study demonstrated that both ABCB1 and ABCC11 were able to confer resistance to eribulin; we also showed that increased expression of both ABCB1 and ABCC11 may be involved in the development of eribulin resistance in breast cancer cells, regardless of the subtype." (PMID 27588398, 2016).
ovarian carcinoma (194 papers, 2009 to 2026). A malignant neoplasm originating from the surface ovarian epithelium. "A recent meta-analysis of 8607 patients confirmed that overexpression of ABCB1 is associated with chemotherapy resistance and poor prognosis in ovarian cancer patients." (PMID 41306963, 2025). "ABCB1 overexpression can be caused by amplification of the gene locus 7q21.12 in neuroblastoma, lung, and ovarian cancers." (PMID 38163893, 2024). "ABCB1 rs1128503 (C1236T) were significantly associated with grade 3-4 anemia in additive model (OR = 1.71; 95% CI: 1.07–2.71; p = 0.023) in 290 ovarian cancer patients." (PMID 39234108, 2024). "Previous research revealed associations of ABCB1 transcript levels with poor outcomes in ovarian cancer, gastric cancer and HCC, whereas inverse trends have been reported for HNSCC and ccRCC." (PMID 35715537, 2022). "Notch signaling has been positively linked to ABCB1 expression in ovarian cancer and cholangiocarcinoma." (PMID 35582031, 2021). "The ABCB1 c.1236C>T homozygous variant genotypes have been associated with less neutropenia in women with ovarian carcinoma receiving either carboplatin plus paclitaxel combination therapy or paclitaxel monotherapy." (PMID 33326171, 2021). "Elevated ABCB1 expression and poor paclitaxel response has also been associated with unfavorable clinical outcomes for ovarian cancer patients." (PMID 34347777, 2021). "From genome-wide screens, we show ABCB1 overexpression consistently associated with paclitaxel resistance across various human ovarian cancer cell line models." (PMID 34347777, 2021). "LncRNA Urothelial Carcinoma Associated 1 (UCA1) is involved in PTX ovarian cancer cell resistance through a miRNA129-ABCB1 (ATP Binding Cassette Subfamily B Member 1) axis." (PMID 33348838, 2020). "Here, in breast and ovarian cancer the authors identify multiple transcriptional fusion partners involving ABCB1 that are associated with treatment failure and previous treatment regimens." (PMID 30894541, 2019). "We discovered that in addition to paclitaxel, TMP195 resensitized KB-V-1 cells and NCI-ADR-RES, an ABCB1-overexpressing MDR variant of OVCAR-8 human ovarian cancer cells, to ABCB1 drug substrates colchicine and vincristine as well." (PMID 31905792, 2019). "According to the whole-genome sequencing data in ovarian cancer, ABCB1 overexpression associated with recurrent promoter fusion was characteristically observed in acquired resistant cases." (PMID 29765522, 2018). "Characteristics of studies that identify ABCB1 mRNA expression and ABCB1 gene variants in epithelial ovarian cancer." (PMID 27812204, 2016). "For the trinucleotide polymorphism (rs2032582) in the ABCB1 gene there was a tendency towards higher ovarian cancer risk for rare TA genotype (OR 5.20; 95%CI 0.87-31.18; p = 0.069)." (PMID 25591549, 2015). "The rs1045642 (3435C > T) synonymous variant in ABCB1 increased 3′p-hydroxy-paclitaxel metabolites in 23 ovarian cancer patients carrying the T-allele." (PMID 25881102, 2015). "However, by blocking the MDR1 glycoprotein encoded by ABCB1, researchers have demonstrated re-sensitization of ovarian cancer cell lines to PARPi." (PMID 35626165, 2022). "Many drug-resistant recurrent ovarian cancers are associated with the upregulation of ABCB1." (PMID 35719392, 2022). "Moreover, the interaction between miR-1246 and caveolin-1 (CAV1) via TDEs caused PTX resistance in ovarian cancer by upregulating the expression of ABCB1, which is the gene encoding P-gp." (PMID 36359776, 2022). "For example, the hypermethylation of CpG island regions covering the distal promoter of the ABCB1 gene might be linked with a lower ABCB1 transcript expression level and longer median OS in breast and ovarian cancer patients." (PMID 33801148, 2021). "Among them, ABCB1 had been reported associated with paclitaxel resistance in ovarian cancer." (PMID 30986993, 2019).